AXL (AXL receptor tyrosine kinase)
Diseases named in the same sentence as AXL in open-access papers (continued):
Sharing a sentence is not in itself a finding about the gene and the disease.
cancer (continued). "Notably, a soluble AXL decoy receptor-Fc fusion molecule, that has been affinity matured for enhanced GAS6 binding over the wildtype soluble AXL (80-fold enrichment), has generated specific and potent antitumor responses as a single agent therapy in preclinical models of cancer." (PMID 27834845, 2016). "Thus, the degradation mechanism of AXL could be a potent target for overcoming gefitinib-acquired resistance in cancer cells." (PMID 25760142, 2015). "Likewise, AXL is overexpressed in colon, thyroid, breast, renal cell, and ovarian cancers." (PMID 23878800, 2013). "We confirmed that the expression levels of AXL and CYR61, target proteins of YAP/TAZ signaling, as well as the expression levels of c-MYC and KLF4, factors representing the cancer cell undifferentiated state, were similarly decreased." (PMID 39604563, 2025). "Upregulation of DDR-related regulators such as GAS6, AXL, HDAC1, and CDK12 restores genomic integrity following chemotherapy-induced damage, allowing cancer cell survival." (PMID 40813689, 2025). "STAT3 involvement in cancer drug resistance is well known, including NB, JAK2/STAT3 signalling can be activated by a variety of RTKs, such as EGFR, MET, or AXL." (PMID 41511287, 2025). "TYRO3, a member of the TYRO3, AXL, and MerTK (TAM) receptor tyrosine kinase (RTK) family, is upregulated in various cancers." (PMID 40299539, 2025). "For example, the potential to restore immunotherapeutic sensitivity to STK11-driven cancers by inhibiting CoREST deacetylase activity has been explored via Tango Therapeutics’ compound TNG26060, or via inhibitors of AXL, CDK4/6, or STAT361–63." (PMID 40791513, 2025). "Bemcentinib, the first selective small-molecule AXL inhibitor to receive US FDA fast-track designation, has shown promising results in combination studies across various cancer types." (PMID 39924521, 2025). "Numerous studies have highlighted the role of AXL signaling in orchestrating DNA damage and DNA damage response (DDR) in drug-resistant cancers." (PMID 39924521, 2025). "We propose a mechanistic model in which dual targeting of CAV1 and AXL impairs the pro-survival signalling via STAT3, AMPKα, and RAC pathways, thereby promoting excessive autophagy and inducing cancer cell death to overcome TKI resistance in HCC." (PMID 40715090, 2025). "Several studies have suggested that AXL plays a vital role in promoting an immune-suppressive TME, which supports cancer progression, metastasis, and resistance to anticancer therapy." (PMID 41471387, 2025). "Growing evidence indicates that upregulated AXL expression promotes resistance to various therapies in NSCLC, acute myeloid leukaemia (AML), breast, colon, GI, head and neck, and other cancers." (PMID 41471387, 2025). "Intriguingly, AXL, the receptor for Spike SARS-CoV2 highly expressed in cancer cells, has been shown to be essential for TGF-β2-induced dormancy of metastatic cancer cells." (PMID 41375068, 2025). "In our initial experiment, we examined the effectiveness of simultaneously inhibiting both AXL and SRC in various cancer cell lines." (PMID 39941857, 2025). "ONO-7475, a dual inhibitor targeting AXL and MERTK, has shown potential in combination therapies for overcoming resistance in various cancers." (PMID 39924521, 2025). "Sitravatinib, a receptor kinase inhibitor targeting TYRO3, AXL, MERTK, and VEGFR2, is being studied in combination with nivolumab for various cancers." (PMID 39924521, 2025). "In HER2+ breast cancer, AXL forms a complex with HER2, promoting its stability and recruitment at the cell surface, thereby promoting the metastatic cascade in cancer progression." (PMID 40560045, 2025). "In addition to ACE2, other membrane proteins may act as Spike receptors (or co-receptors) for SARS-CoV2 among which we only mention AXL, Neuropilin-1, and CD147 that are highly expressed on cancer cells and might explain the increased susceptibility of cancer patients to infection." (PMID 41375068, 2025).
cancer (continued). "In conclusion, the results from this study support the therapeutic potential of dual inhibition of AXL and SRC towards KRAS mutant NSCLC therapies and will aid in our understanding of molecular mechanisms behind TKI therapies in KRAS mutant harboring cancers." (PMID 39941857, 2025). "The widespread relevance of the FRA1 transcriptional network is evident across multiple aggressive cancer types, where FRA1 expression correlates with AXL, CDK6, and FSCN1 levels and poor patient outcomes." (PMID 41286309, 2025). "It prevents direct AXL/AXL or GAS6/GAS6 interactions, influencing processes such as epithelial-to-mesenchymal transition (EMT), a key event in cancer progression." (PMID 39924521, 2025). "This cancer highly expresses MET and AXL, and the combination of NPS-1034 with the commonly prescribed anti-PDAC chemotherapies oxaliplatin and fluorouracil shows a remarkably effective synergistic effect." (PMID 39000029, 2024). "Since the binding of GAS6 to AXL has been found to promote cancer progression and sdAb20 was predicted to interact with the GAS6 recognition site, we further evaluated the GAS6/AXL blocking capacity of sdAb20 in vitro using a competition assay." (PMID 38773967, 2024). "Our results warrant further development of S6K1-targeting strategies in combination with AXL inhibition to overcome signaling redundancy mediated by S6K2 in GBM and other cancers frequently affected by PTEN inactivation." (PMID 39087397, 2024). "Mer‐tyrosine kinase (MERTK), a member of the AXL, TYRO3, and MERTK (TAM) family, is one of the promising targets for cancer treatment." (PMID 39635932, 2024). "To detect the C-mannosylation of AXL in other cell lines, we established AXL-ECD-overexpressing cells, purified recombinant AXL-ECD, and performed LC–MS/MS analysis in 3 cancer cell lines: human NSCLC PC9 and H3122 and human fibrosarcoma HT1080." (PMID 39660536, 2024). "The role of AXL in phosphorylating key substrates, like MIG6, shows its influence in pathways critical to tumorigenesis and cancer cell survival." (PMID 39597836, 2024). "In vitro, AXL inhibitors, such as TP-0903 or R428 (BGB324), reversed EMT and restored drug sensitivity in several cancer types, including TNBC16–20." (PMID 38172210, 2024). "These preclinical data also provided the basis for the clinical trials with AXL inhibition and ICI-based therapy in cancer patients." (PMID 38310091, 2024). "This newly established AXL+ CTC assay is a promising tool that can be used for liquid biopsy in future clinical trials to stratify and monitor patients with cancer receiving anti‐AXL therapies." (PMID 38132919, 2023). "AXL and its ligand, i.e., growth arrest-specific 6 (GAS6) proteins axis is reported to promote cancer cell proliferation, survival, migration, invasion, and immune evasion." (PMID 36823234, 2023). "AXL signaling primarily promotes invasion, while EGFR signaling favors proliferation, and their interaction contributes to cancer metastasis." (PMID 37834326, 2023). "In preclinical evaluations, Axl, a receptor tyrosine kinase that is part of the TAM (TYRO3, AXL, and MER) family, was shown to have several roles in cancer development including cell growth, adhesion, survival, and proliferation." (PMID 37370772, 2023). "Mechanistic details are complex and pleiotropic, however, because these receptors, especially AXL and MER are known to be active in cancer cells, in addition to their activities in macrophages and other cell types in the TME." (PMID 37553811, 2023). "In fact, their associations (SCARB1 most in all investigated 33 cancers, followed by NRP1 in 31 cancers, TMPRSS2 in 27 cancers, AXL in 25 cancers and ACE2 in 13 cancers) appeared in more cancer types than those of CNVs with the same trends among the five STGs." (PMID 36875081, 2023).
cancer (continued). "The selective inhibitor ONO-7475, which targets MER, AXL, and FLT3, is in Phase I clinical trials for advanced solid tumors and acute leukemia after suppressing progression of both forms of cancer in preclinical models." (PMID 37936688, 2023). "Since GI cancer mesenchymal cells exhibit high levels of AXL expression, this RTK is potentially a promising therapeutic target for overcoming chemoresistance and improving the efficacy of current cancer therapies." (PMID 37469409, 2023). "Treatment with AXL and MET inhibitors successfully abolished Galectin-1 overexpression–mediated cancer stemness." (PMID 37433225, 2023). "AXL, an RTK, plays a variety of functions in normal cells, and its overexpression predicts worse outcomes in various types of human cancers." (PMID 35805163, 2022). "For AXL, relative expression data in PTC and cancer-adjacent tissues were analysed using a t-test or one-way ANOVA and the Mann‒Whitney U- or Kruskal‒Wallis H-test, in SPSS 25.0." (PMID 36203174, 2022). "Cabozantinib is used for cancer treatment and inhibits various receptor tyrosine kinases, including VEGFR, MET, RET, KIT, AXL and FLT332." (PMID 35449173, 2022). "Once activated, AXL autophosphorylation stimulates the downstream signaling pathways such as PI3K/AKT, MAPK, and JAK/STAT, therefore, controlling the cancer cell activities." (PMID 35414783, 2022). "EGFR, HER2, ALK, AXL, FLT3, PDGFR and other receptors and signal transducers (e.g., Raf) are involved in the metastasis of various cancers." (PMID 35477123, 2022). "AXL (Ark or UFO) is a member of TAM family of receptor tyrosine kinase, which is highly expressed in cancers." (PMID 35875329, 2022). "We discuss future directions with the aim to understand better the complex role of AXL and TAM receptors in cancer and the potential value of this knowledge and targeted inhibition for the benefit of cancer patients." (PMID 35572601, 2022). "It is well acknowledged that EMT is a key driver of cancer metastasis, but EMT also can override the cytostatic effects of anti-EGFR therapy by increasing Snail and AXL expression." (PMID 35279145, 2022). "In human carcinoma cells MDA-MB-231, HeLa, and MCF7, PD-L1 expression was shown to be upregulated by hyperactive MERTK and AXL signaling." (PMID 35572601, 2022). "Among them, AXL and MER are known proto-oncogenes and have been confirmed to be overexpressed in several cancer types." (PMID 34721022, 2021). "Recently, AXL and TIMD4 have also been reported to be positively correlated to the poor progression of many cancers." (PMID 34778091, 2021). "Multiple signaling pathways involved in cancer initiation and progression, including the EGFR, VEGFR, focal adhesion and RAS signaling pathways, can be rapidly activated after the activation of AXL signaling." (PMID 34439388, 2021). "In four large data sets of cancer patient cohorts (MSK-IMPACT, TCGA, METABRIC, and GENIE), alterations in AXL are observed." (PMID 33850249, 2021). "In cancer cells, GAS6-activated AXL induces multiple actin-dependent cytoskeletal rearrangements that jointly contribute to invasion." (PMID 34310342, 2021). "Even more striking was the upregulation in dCTCs of AXL, an RTK known to mediate YAP/TAZ oncogenic effects, OS metastasis, and chemoresistance in several cancer types." (PMID 33408328, 2021). "Drugs targeting AXL, a downstream effector of YAP/TAZ found in numerous cancer types, are being explored in the preclinical setting." (PMID 33408328, 2021). "AXL, a member of the TAM receptor family, is strongly activated in many different cancer types and was shown to drive resistance of AML cells to FLT3 inhibitors via signals from the stromal microenvironment and the activation of STAT5." (PMID 34944800, 2021). "AXL and its ligand, i.e., growth arrest-specific 6 (GAS6) proteins, are expressed on many cancer cells, and the GAS6/AXL pathway is reported to promote cancer cell proliferation, survival, migration, invasion, angiogenesis, and immune evasion." (PMID 34778071, 2021).
cancer (continued). "AXL also plays an important role in epithelial to mesenchymal transformation (EMT), and cell invasion and migration, highlighting its role in cancer metastasis." (PMID 34442532, 2021). "The role of AXL-RTK in developing resistance to therapies is well-known and well-studied in different cancers." (PMID 34140003, 2021). "For colony-forming assay cancer cells were seeded in multi-well plates at clonal density and treated with the TGFBR1 inhibitor galunisertib and/or the AXL inhibitor." (PMID 33570712, 2021). "Recent research supports the role of Hippo signaling in the modulation of cancer-cell proliferation and human tumorigenesis by transcriptional regulation of several cell proliferation-related genes, such as AREG, AXL, CTGF, CYR61, and VEGFA." (PMID 32365528, 2020). "In this study, we conducted cell migration and invasion assays under serum-free conditions, using GAS6 or HGF as chemoattractants to dissect the roles of AXL and MET in cabozantinib-mediated inhibition of cancer cell migration and invasion." (PMID 32055714, 2020). "To identify the potential downstream component of the GAS6/MER pathway, we compared the expression of MER, AXL, and TYRO3 among various human cancer cell lines including HeLa, DU145, THP-1, RKO, SKM1, A549, OCI-LY3, G361, and HL60." (PMID 32042425, 2020). "Stiffening CSCs via AXL inhibition is a critical mechanism of the multiple benefits provided by EGCG, including preventing cancer, inhibiting metastasis, and overcoming chemoresistance." (PMID 32051483, 2020). "We believe the profile of INCB081776 as a selective inhibitor of AXL and MERTK will provide an attractive potential treatment option for patients with cancer not only as a single agent, but also in rational combination with immunotherapeutic agents." (PMID 33425754, 2020). "Here, we discussed the results of AXL activation; however, PTP4A in human cancers should be considered in future studies." (PMID 32051483, 2020). "At present it is not well known how expression of AXL and TYRO3 is regulated; given the emerging role of TAM RTKs in cancer and drug response however, this is an area of active research." (PMID 33059733, 2020). "By performing an AXL phosphoproteomic screen, we explain how this RTK facilitates cancer cell invasion and metastasis by strongly modulating the biological process of FA turnover." (PMID 32681075, 2020). "Like AXL, PEAK1 expression correlates in many cancer models with mesenchymal features, disease relapse, and therapy resistance." (PMID 32681075, 2020). "Members of the TAM family of RTKs (TYRO3, AXL and MER) have emerged as attractive targets for cancer therapy, and they have received a great deal of attention for ICB combination due to their suppressive functions in innate immune cells." (PMID 35582229, 2020). "AXL was aberrant and was involved in epithelial-mesenchymal transition (EMT) in various cancers, including NSCLC." (PMID 31948451, 2020). "Targeting AXL holds great therapeutic potential to diminish WNT/â-catenin and TGFâR signalling and sphere formation ability, and therefore, to repress cancer resistance and progression." (PMID 31684958, 2019). "Because AXL is considered an important molecular target in cancer therapy, various strategies, like sAXL decoy receptor (GL2I.T and MYD1–72) and antagonistic monoclonal antibody targeting AXL (YW327.6S2 and 20G7-D9) are currently in preclinical development." (PMID 31171001, 2019). "These include the ECM component fibronectin and AXL, a receptor tyrosine kinase that transmits signals from the ECM to regulate adhesion, migration, and survival of cancer cells." (PMID 30388137, 2018). "Overall, these observations strongly suggest that pathways downstream of BRAF and AXL are responsible for RIPK3 expression suppression and escape from necroptosis in cancer." (PMID 30157175, 2018). "The TAM receptors Tyro3, AXL, and MERTK are oncogenic drivers that promote survival, chemoresistance, and motility of cancer cells." (PMID 29382817, 2018).
cancer (continued). "AXL activation and EMT features have also been reported as mechanisms of resistance to targeted therapy in human cancers, including NSCLC." (PMID 29930762, 2018). "The receptor tyrosine kinases (RTKs) TYRO3, AXL and MERTK (TAM) have well-described oncogenic functions in a number of cancers." (PMID 28727830, 2017). "The mechanism of YAP1-promoted resistance includes activation of the receptor tyrosine kinase AXL, the apoptosis inhibitor Survivin (BIRC5) genes, and autophagy depending on different drugs in different cancers." (PMID 27911857, 2017). "Final clinical study results upon completion of the trials would provide insights into the potential significance of AXL inhibition in NSCLC and other human cancers." (PMID 28551766, 2017). "Deregulation of the TAM (TYRO3, AXL, and MERTK) family of receptor tyrosine kinases (RTKs) has recently been demonstrated to predominately promote survival and chemoresistance of cancer cells." (PMID 28034848, 2017). "The overexpression and hyperactivation of members of the TAM family of receptor tyrosine kinases – comprising TYRO3, AXL and MERTK is documented in many cancers." (PMID 28118606, 2017). "AXL, a receptor tyrosine kinase is a member of the TAM (Tyro-Axl-Mer) family, that is overexpressed and activated in various human cancers and is correlated with poor prognosis in patients." (PMID 27590506, 2016). "AXL is a tyrosine kinase receptor activated by GAS6 and regulates cancer cell proliferation migration and angiogenesis." (PMID 25966280, 2015). "The aim of the study was to evaluate AXL and cellular mesenchymal-epithelial transition factor (C-MET) biomarkers for cancer stem cells and to correlate them with clinicopathological characteristics and patient outcome data with respect to neoadjuvant chemoradiotherapy." (PMID 41563267, 2026). "Although a few selective small-molecule AXL inhibitors have been evaluated in clinical trials, no selective AXL inhibitor has been approved for the treatment of any type of cancer." (PMID 41471387, 2025). "Thus, we wanted to see if TKI‐mediated AXL upregulation and activation also occurs in other RTK‐driven cancers that exhibit pERK rebound." (PMID 39395205, 2025). "AXL, a member of the TAM kinase family and a receptor for growth arrest-specific protein 6 (GAS6), is known to contribute to invasion, inhibition of apoptosis, increased proliferation, and chemoresistance in various cancers." (PMID 41511287, 2025). "Similarly, OPCML’s repression of AXL, also in synergy with selective inhibitors, can more effectively target EMT in cancer cells, especially as an approach to overcome resistance to prior chemotherapies." (PMID 40699804, 2025). "Inhibition of AXL and SRC led to increased levels of pro-apoptotic proteins in cancer cells." (PMID 39941857, 2025). "It was observed that STAMBPL1 KD markedly reduced the abundance of AXL without affecting AXL RNA levels in primary cancer cells." (PMID 39527690, 2025). "In addition, the combination of AXL inhibitor with WIN55212-2 treatment exhibited an increase in cytotoxic T lymphocytes, leading to cancer death." (PMID 39598377, 2024). "Dual AXL/MERTK inhibitors such as ONO-7475, INCB081776, CT413, PF-07265807, and Q702, as well as pan-TAM inhibitors like RXDX-106, BMS-777607, and LDC1267, have also been found to be effective in cancer models." (PMID 39062902, 2024). "They demonstrated that AXL activation triggers actin remodeling, leading to the formation of peripheral membrane ripples, circular dorsal ripples (CDRS) and micropinocytosis, contributing to the invasion and metastasis of cancer cells." (PMID 38391974, 2024). "While relatively less is known about the role of TYRO3 in cancer, targeting MER and AXL may be advantageous." (PMID 37936688, 2023). "AXL could be transactivated by EGFR in cetuximab–resistant cells and may serve as a potent target in advanced cancer therapy." (PMID 37834326, 2023).